APC (APC regulator of Wnt signaling pathway)
Diseases named in the same sentence as APC in open-access papers (continued):
Sharing a sentence is not in itself a finding about the gene and the disease.
tumor (continued). "Adenomatous Polyposis Coli (APC) is a tumor suppressor gene product involved in cellular processes including Wnt signaling, cell growth, cell fate determination and cell migration." (PMID 21311754, 2011). "Two-way hierarchical clustering in serum and tumor tissue showed significant hypermethylation patterns of seven genes (APC, BIN1, BMP6, BRCA1, CST6, P16 and TIMP3) compared with normal tissue." (PMID 21283676, 2011). "The APC tumour suppressor functions in several cellular processes including the regulation of β-catenin in Wnt signalling and in cell adhesion and migration." (PMID 21152425, 2010). "The subpopulation of phospho-β-catenin at the microtubule tips appears to play a role in the tumour suppressor function of APC." (PMID 21152425, 2010). "While RASSF1A mRNA levels were found downregulated in all tumours investigated, APC gene expression was retained through APC 1B mRNA levels." (PMID 20208994, 2010). "Synthetic cancer vaccines, offer safety, reliability and cost advantages over traditional methods (e.g. live vectors, tumor cells-APC fusions, genetic immunization), but formidable challenges still confront their development." (PMID 20574522, 2010). "In our study, a total of 39 out of 55 tumours (71%) were considered to exhibit a hypermethylated APC promoter 1A (above 10% density) as compared to the 16 tumours (29%) with very low methylation (below 10% density)." (PMID 20208994, 2010). "The identified genes are involved in drug transport and detoxification (ABCB1, DNAJC15, GSTP1, RAB6C), DNA damage repair (BRCA1) as well as tumor cell proliferation/invasion (APC, CDH1, ESR1, HIC, PLAU, RASSF1, SULF2, TGM2)." (PMID 20544021, 2010). "Mitochondrial localization of the endogenous APC mutants with sequence 1-1309 correlated with tumor cell survival, i.e. reduced apoptosis." (PMID 20591184, 2010). "The APC tumour suppressor provides a particularly good model for study, because multiple tumours are available from FAP patients, LOH generally occurs only in a restricted set of cases, and LOH usually takes the form of mitotic recombination." (PMID 19515250, 2009). "We extended our tumor analysis with an independent genetic mouse model for CRC by crossing Atoh1Δintestine mice to APCmin mice (APC: ENSMUSG00000005871), in which Wnt signaling is constitutively activated." (PMID 19243219, 2009). "In general, as a result of these selective constraints on APC in early tumours, LOH at APC occurs by mitotic recombination (break-induced replication), causing reduction to homozygosity but no copy number change." (PMID 19515250, 2009). "Since the selective constraints on APC require two mutant copies in the early tumour cell, chromosome breaks must occur between the centromere and APC, and hence be repaired by break-induced replication." (PMID 19515250, 2009). "Notwithstanding its multifunctional nature, the main tumor suppressing activity of the APC gene resides in its ability to regulate Wnt/β-catenin signaling." (PMID 19578404, 2009). "In view of the well known multifunctional nature of the APC tumor suppressor protein, one could also envisage that functional motifs other that those binding and downregulating β-catenin and Axin, could underlie the striking tumor phenotype of the Apc1572T model." (PMID 19578404, 2009). "In one patient, was detected a deletion of exon 13th of APC gene both in DNA extracted from blood and tumor samples." (PMID 20108522, 2008). "PMR values for APC were significantly elevated in tumour compared with matched normal breast tissue (P=0.022; Wilcoxon signed-rank test)." (PMID 18841156, 2008). "It should be emphasised that more investigation is required to determine to what extent the epigenetic inactivation of APC affects the biological behaviour of these tumours." (PMID 18841156, 2008).
tumor (continued). "A key effector of this pathway is β-catenin, which is normally phosphorylated and targeted for degradation by the Axin complex that also contains the Adenomatous polyposis coli (APC) tumor suppressor." (PMID 18627596, 2008). "The median level of APC methylation was 3.27 (range, 0.01–94.31) in tumour compared with 0.29 (range, 0–26.35) in matched normal tissue." (PMID 18841156, 2008). "Epigenetic CpG-island hypermethylation of the promoter region has been proposed as an alternative way to inactivate the APC tumour suppressor gene." (PMID 18841156, 2008). "For RASSF1A, CCND2, GSTP1, TWIST, and APC genes, the proportion of methylated genes was significantly higher in the ER-positive than in the ER-negative tumor group." (PMID 18485221, 2008). "In the Apc/Min mouse lackingfunctional APC protein as well as in azoxymethane-induced intestinalcarcinogenesis, effects of PPARβ/δ have been described for tumor growth with different outcomes." (PMID 18497874, 2008). "Several tumour types have also shown aberrant methylation at the CpG island in other genes, including the FAP-associated gene APC, detoxifying gene GSTP1, DNA repair gene MGMT, the potential metastasis inhibitor gene DAP-kinase, and Rb interact gene RIZ1." (PMID 17968429, 2007). "Promoter hypermethylation in 10 tumour-related genes (APC, E-cadherin, GSTP1, hMLH1, MGMT, p15, p16, SOCS1, TIMP3 and TGF-beta RII) was determined by quantitative methylation-specific PCR (MethyLight)." (PMID 15942635, 2005). "We have shown that many tumour suppressor and tumour-related genes, such as APC, DAP-kinase, DCC, E-cadherin, hMLH1, p16, RASSF1A and RUNX3, exhibit promoter hypermethylation in both neoplastic and non-neoplastic gastric epithelia at variable frequencies." (PMID 15138487, 2004). "In several tumour types, TCF/β-catenin activation is caused by mutations in either adenomatous polyposis coli (APC), β-catenin exon 3, AXIN1, AXIN2 or β-transducin repeat-containing protein (β-TrCP)." (PMID 14970870, 2004). "In the absence of activating WNT signals, β-catenin is phosphorylated by a multiprotein complex containing GSK3β, the tumour suppressors APC and axin/conductin." (PMID 12799639, 2003). "It has also been shown that elimination of MMPs or COX-2 by either genetic strategies or with inhibitors results in a decrease in the number of tumours formed in mice with altered APC function." (PMID 12778076, 2003). "By this criterion APC, GSK3β, and axin are potent tumor suppressors, whereas β-catenin is an oncogene." (PMID 14551908, 2003). "LOH on 5q occurred at the sites of the MSH3 mismatch repair gene and the APC tumour-suppressor gene." (PMID 9764589, 1998). "We examined allelic imbalance at the locus of the tumour-suppressor gene, APC (adenomatous polyposis coli), on chromosome 5q using a polymerase chain reaction (PCR)-based assay." (PMID 8980382, 1996). "Allelic imbalance at three additional loci on chromosome 5 was demonstrated in tumours that exhibited AI at the APC locus, suggesting that endoreduplication of chromosome 5 had occurred." (PMID 8980382, 1996). "High levels of miR-129 correlate with reduced postoperative survival and may contribute to tumor progression by targeting tumor suppressors such as APC and RAB11." (PMID 41596525, 2026). "The increased prevalence of APC mutations in H/L patients suggests that WNT pathway activation may serve as a distinct molecular driver in this population, which could influence tumor aggressiveness and treatment response." (PMID 40227587, 2025).
tumor (continued). "Among these genes, APC is a tumor suppressor that regulates the Wnt signaling pathway." (PMID 40422048, 2025). "Furthermore, expression levels of APC and GSK-3 β were notably increased in cells treated with BITC compared to the control cells, which was also further evidenced by increased levels of APC in the tumor samples of the BITC treatment group." (PMID 40001961, 2025). "In addition, some studies have found that GSK-3β is part of a tumor suppressor complex consisting of Axin and APC that phosphorylates the oncoprotein β-catenin." (PMID 40157890, 2025). "In conclusion, multiple CRC-associated DNA methylation changes distinguished FAP normal colon mucosa paired to tumor, suggesting that DNA methylation may play a crucial role in field cancerization in APC-driven tumorigenesis." (PMID 40753397, 2025). "In addition to overexpression of β-catenin, knocking down the APC gene in APC-mutant CRC also leads to tumor cell death." (PMID 40240755, 2025). "Similarly, miR-155 contributes to tumor progression by targeting APC, thereby disrupting Wnt signaling and enhancing proliferation and invasion." (PMID 40943532, 2025). "By contrast, the predominance of APC truncations in LOCRC supports a canonical mode of pathway disruption that may develop over longer tumor latency periods." (PMID 40940930, 2025). "We used spatial transcriptome data from intestinal tumor tissues of APC Min/+ mice." (PMID 41009818, 2025). "Using “tumor-informed” approach, reaching a detection limit of around 1%, the mosaic APC variant was not detectable in leukocyte, urine, and buccal swab DNA." (PMID 40956995, 2025). "Loss of adenomatous polyposis (APC) leads to excessive activation of LGR5+ stem cells, resulting in adenocarcinoma formation, indicating that LGR5+ intestinal stem cells (ISCs) are an important source of tumor cells." (PMID 41488637, 2025). "In non-tumor cells, APC protein is distributed evenly between the nucleus and cytoplasm, but in approximately 80% of CRC patients, APC mutations result in accumulation of a truncated, stable protein within the nucleus, disrupting normal transport mechanisms and promoting WNT pathway dysregulation." (PMID 41009818, 2025). "APC is central to the Wnt signaling pathway, and its mutation leads to uncontrolled cell proliferation, while PIK3CA mutations activate the PI3K-Akt pathway, which promotes tumor cell survival and growth." (PMID 40936932, 2025). "Intestinal stem cells act as a homeostatic balance but promote cancer stem cells in intestinal tumorigenesis when Β-catenin in intestinal stem cells is activated, stimulating the development of CRC due to inhibition of the adenomatous polyposis coli (APC), a tumor suppressor gene." (PMID 40869407, 2025). "While most of the single-hit tumours were APC-driven, this accounted for only 3% of all tumours." (PMID 39920335, 2025). "Notably, as one of the key signaling effectors of integrins, focal adhesion kinase (FAK) has been shown to drive tumor onset and growth in the adenomatous polyposis coli protein (APC)‐null mouse model." (PMID 40959971, 2025). "In individuals with wild-type APC genes, the two functional proteins undergo homodimerization and interact with the β-catenin destruction complex to enable its proper function, a critical step in tumor suppression." (PMID 40695959, 2025). "APC, a tumor suppressor gene, is involved in the regulation of the Wnt signaling pathway." (PMID 40507920, 2025). "As a tumor suppressor, APC regulates β-catenin’s adhesion function." (PMID 40641920, 2025).
tumor (continued). "Additionally, the mutation profiles differ, with right-sided tumors more frequently showing BRAF mutations, while left-sided tumors show higher rates of APC and KRAS mutations.5) Moreover, responses to systemic therapy vary based on tumor location." (PMID 41139484, 2025). "Similarly, WNT pathway alterations—particularly in CTNNB1 and APC—were enriched in H/L patients with PC and GC, reinforcing their potential role in driving tumor biology in this population." (PMID 40869017, 2025). "Moreover, the negative correlation that we observed between retained 20AAR number and AXIN2 expression suggests that the APC genotype acquired early in tumorigenesis has lasting consequences on WNT levels throughout tumor progression." (PMID 41091816, 2025). "In addition, METTL3, an RNA methyltransferase, has been described to facilitate tumour development by reducing the expression of APC (Adenomatous Polyposis Coli), a tumour suppressor gene." (PMID 40603707, 2025). "Another tumor suppressor gene involved in the WNT pathway is APC." (PMID 40080754, 2025). "METTL3 depletion increased APC expression and reduced tumor size of athymic nude mice." (PMID 38721006, 2024). "Similarly, enriched LOH events covered tumour suppressor genes such as APC (5q22.2), ATM (11q22.3), and CDX2 (13q12.2)." (PMID 39461959, 2024). "APC (p = 1.7e-20), BCL9 (p = 0.0006), CREBBP (p = 8.5e−5), FLCN (p = 1.39e−7), NSD2 (p = 0.002), and EP300 (p = 1.42e−6) all had significantly higher mutation rates in MSLN low expressing tumor samples compared to MSLN high expressing tumor samples." (PMID 39174744, 2024). "We chose triple negative breast tumor resection specimens as the test substrate and selected three panels (Tact, PD-L1 and APC) directed against human antigens that identify and localize cell populations that are important to the pathogenesis and treatment of neoplastic diseases." (PMID 38605049, 2024). "Tumor pathogenesis includes STK11, APC, and MDB4 mutations as well as KMT2D variants, which are of unknown biological significance." (PMID 40034930, 2024). "It implies that the dysregulation of the Wnt/β-catenin pathway due to APC mutations might play a pivotal role not only in nuclear β-catenin accumulation but also in orchestrating the EMT process, a hallmark of tumor invasiveness and metastasis." (PMID 38414697, 2024). "While inducing APC loss resulted in tumors both in the cecum and along the colon of mice, YWF administration reduced the size of the main cecal mass, as well as the number and size of the smaller neoplasms along the colon." (PMID 39266717, 2024). "APC mutations are central in predicting OS, and patients with tumours without APC mutation have worse prognosis than those with single somatic APC mutations." (PMID 39263143, 2024).
tumor (continued). "Tregs contribute to T-cell exhaustion, inhibiting anti-tumor responses through various mechanisms, including APC inhibition, cytokine depletion, and production of immunosuppressive factors, ultimately promoting tumor proliferation, and reducing responses to immunotherapies." (PMID 38891056, 2024). "The sustained PR and continuous absence of APC mutations indicate a positive clonal shift, where less aggressive or more immunogenic tumor subclones dominate, maintaining efficacy over time." (PMID 39796090, 2024). "Lastly, we find that reduced APC expression is associated with APA dysregulation in tumor types lacking recurrent APC mutations." (PMID 39375704, 2024). "The APC tumor suppressor gene is involved in the APC/β-catenin/Tcf pathway." (PMID 39031216, 2024). "Indeed, this is reminiscent of the conversion of the canonical WNT and STAT3 signaling pathways in the context of mutant APC-driven tumor formation in the colonic mucosa." (PMID 39128004, 2024). "Although the exact mechanism of upregulation of KLK6 and other proteases in the presence of APC mutations is not completely understood, our study contributes to the recognition of KLK6’s role in tumor development and demonstrates a possibility for using KLK6 for CRC detection and therapy." (PMID 39594797, 2024). "Loss of APC function, resulting from mutations or deletion, leads to increased β-catenin levels and persistent activation of the WNT signaling pathway, which can trigger genomic instability and promote tumor development." (PMID 39021676, 2024). "The lack of APC tumor suppressor function due to mutation causes a rise in the β-catenin protein level in cells and its translocation to the nucleus, where it serves as a transcriptional coactivator of cell proliferation genes such as the C-MYC oncogene." (PMID 39594797, 2024). "Vice versa, despite a relatively high AF, only two mutations were exclusively detected in tumor biopsies (VPS13B (vacuolar protein sorting 13 homolog B), AF 0.09, Pat ID 1385 and APC, AF 0.2, Pat ID 1364), compared to 15 and 6 mutations that were detected only in plasma or stool, respectively." (PMID 38766867, 2024). "Theoretically, detecting such genomic abnormalities using IHC is powerful evidence of neoplasm, but, unfortunately, IHC methods that reliably detect APC mutation have not been developed yet." (PMID 39451200, 2024). "Consequently, APC-truncated tumour cells accumulate the co-activator β-Catenin, which translocates to the nucleus, displaces the TLE co-repressor and associates with the transcription factor TCF-4/LEF-1 to promote the expression of WNT pathway target genes." (PMID 39443725, 2024). "Whether APC migration from the tumor to the TdLN or whether antigen passively drains to the node following RT is an area of active investigation and the focus of future studies." (PMID 38496632, 2024). "Somatic variants in APC and CTNNB1 were unique to each tumor." (PMID 38725616, 2024). "In the present case, the tumor was probably associated with a heterozygous mutation in APC because of the patient's history of FAP; however, we did not perform a genetic marker test." (PMID 39588447, 2024).